SLC39A8 (solute carrier family 39 member 8)
Diseases named in the same sentence as SLC39A8 in open-access papers (continued):
Sharing a sentence is not in itself a finding about the gene and the disease.
glioblastoma (3 papers, 2021 to 2025). The most malignant astrocytic tumor (WHO grade IV). "The expression of Slc39a8 (Zip8) was detected in DI TNC1 astrocytes, but significantly (unpaired t-test: p = 0.0038) less expression was detected in C6 glioblastoma cells, a finding that may have relevance for the pathomechanisms of glioblastomas." (PMID 33925953, 2021). "Additionally, SLC39A8 exhibited significant overexpression in adrenocortical carcinoma (ACC), COAD, DLBC, ESCA, glioblastoma multiforme (GBM), KIRP, READ, STAD, TGCT, THYM, and UCEC, while its downregulation was observed in LUAD and LUSC." (PMID 38230214, 2024).
glycosylation disorders (3 papers, 2019 to 2021). "In contrast to other glycosylation disorders, SLC39A8-CDG is caused by mutations in the gene encoding the eponymous divalent cation channel, that acts as the principal cellular manganese uptake transporter." (PMID 34567084, 2021).
idiopathic scoliosis (3 papers, 2018 to 2025). A scoliosis with no known cause. "Several genetic loci, including SLC39A8 and ABO, have been established as significantly associated with adolescent idiopathic scoliosis risk in the Han Chinese population." (PMID 41211406, 2025).
insomnia (3 papers, 2019 to 2026). A sleep disorder characterized by difficulty in falling asleep and/or remaining asleep. "Fine-mapping and colocalization analyses identified shared genetic signals between cannabis use and clinical insomnia including a near-perfect colocalization at SLC39A8 and CADM2." (PMID 42064962, 2026).
lung disease (3 papers, 2020 to 2025). "GWAS have associated SLC39A8 gene variations with pathologies in multiple systems, such as dysmorphogenesis and immune, cardiovascular, gastrointestinal, coagulation, musculoskeletal, central nervous system, eye, kidney, and lung disorders." (PMID 36986146, 2023). "Moreover, genetic screening for SLC39A8 and POC5 may provide insight into patient stratification and inform the development of targeted interventions aimed at immunological and inflammatory pathways in lung disease." (PMID 40869120, 2025).
lymph node metastasis (3 papers, 2020 to 2024). "The results indicated that the expression of SLC39A8 in patients with distant metastasis or lymph node metastasis was significantly decreased, and the prognosis of those patients with decreased expression of SLC39A8 was significantly worse." (PMID 33869056, 2021). "Notably, SLC39A8 exhibited significant expression differences in cases of lymph node metastasis and distant metastasis in CRC patients." (PMID 39006076, 2024). "For patients with positive lymph node metastasis, SLC39A2, SLC39A3, SLC39A7, SLC39A8, SLC39A12 and SLC39A13 high expression suggested a worse OS, but SLC39A10 high expression suggested a benefit OS." (PMID 32744318, 2020).
age-related macular degeneration (2 papers, 2023 to 2024). Age-related loss of vision in the central portion of the retina (macula), secondary to retinal degeneration. "Transcriptomic analyses have shown an upregulation of Slc39a8 in patients with AMD (Age-related Macular Degeneration)." (PMID 38812011, 2024).
Cerebral atrophy (2 papers, 2021). Atrophy (wasting, decrease in size of cells or tissue) affecting the cerebrum. "In patients with SLC39A8 mutations, cerebral atrophy is present and T2-weighted MRI differences are observable in basal ganglia." (PMID 33790950, 2021).
chronic kidney disease (2 papers, 2024 to 2025). Impairment of the renal function secondary to chronic kidney damage persisting for three or more months. "Recent studies have reported increased tubular iron deposition in patients with chronic kidney disease with elevated Slc39a8 levels." (PMID 38812011, 2024).
Clear Cell Renal Cell Carcinoma (2 papers, 2021 to 2022). "SLC39A8 suppresses the progression of clear cell renal cell carcinoma." (PMID 36499305, 2022).
cognitive deficits (2 papers, 2018 to 2024). "Recessive mutations of SLC39A8 were recently shown to cause cognitive impairment, epilepsy, hearing loss, and skeletal abnormalities that include short limbs and scoliosis." (PMID 30301978, 2018). "In PheWAS, we also find that SLC39A8 is associated with the cognition test scores (i.e., fluid intelligence and prospective memory), which aligns with the known characteristics of AD as a progressive neurodegenerative disorder characterized by memory loss and cognitive deficits." (PMID 38956042, 2024).
colon adenocarcinoma (2 papers, 2024 to 2025). "This process yielded a four-gene signature—PDSS2, GRSF1, SLC39A8, and P4HA1—with significant prognostic value in colon adenocarcinoma." (PMID 40959429, 2025). "In the human colon adenocarcinoma HCT-15 and duodenal adenocarcinoma HuTu80 cell lines, we generated clones with knockouts of the SLC39A8 and SLC39A14 genes and forced overexpression of the SLC30A3, SLC30A10, and SLC39A8 genes." (PMID 39596116, 2024).
coronary artery disease (2 papers, 2019 to 2021). "The first GWAS to report a SLC39A8 variant appeared in a meta-data analysis of 15 combined studies, comprising >55,000 participants; moreover, authors screened for correlations between SNVs at “lipid-related” loci and risk of coronary artery disease in ~9600 cases and ~38,600 controls." (PMID 31521203, 2019).
COVID-19 (2 papers, 2024 to 2025). A disease caused by infection with severe acute respiratory syndrome coronavirus 2. "The most significant topSNP between COVID-19 and chronic pain was rs13135092, which mapped genes SLC39A8 and BANK1." (PMID 38633255, 2024). "The second locus, with a PPH4 of 98.12% in critical COVID-19, was mapped to the BANK1 and SLC39A8 gene, also situated on chromosome 2." (PMID 38633255, 2024).
depression (2 papers, 2016 to 2025). "In total, these findings suggest that SLC39A8 and CTNNB1 might contribute to psychogenic ED through changes invoked in the amygdala, and provide a possible mechanism for the moderate genetic correlations we found for EHR-ED with depression and PTSD." (PMID 41285899, 2025).
epilepsy (2 papers, 2018 to 2025). A brain disorder characterized by episodes of abnormally increased neuronal discharge resulting in transient episodes of sensory or motor neurological dysfunction, or psychic dysfunction. "Although SLC39A8 has not been directly associated with DEE, mutations in this gene can cause manganese deficiency, which has been linked to epilepsy." (PMID 40167904, 2025).
hepatoma (2 papers, 2018 to 2020). "SLC39A8 encodes a member of the SLC39 family of solute-carrier genes (Zrt/Irt-like protein 8, ZIP8), which may play an important role in autophagy during ethanol exposure in human hepatoma cells." (PMID 32393195, 2020).
left ventricular noncompaction (2 papers, 2019 to 2024). Left ventricular noncompaction (LVNC) is a rare cardiomyopathy characterized anatomically by prominent left ventricular trabeculae and deep intratrabecular recesses causing progressive systolic and diastolic dysfunction, conduction abnormalities, and occasionally thromboembolic events. "While attempting to characterize the UBC>Cre>ERT2>Slc39a8(fl/fl) Slc39a8(−/−) global knockout, it was discovered that before early-embryonic death, the mice show a cardiac phenotype similar to human left ventricular noncompaction (LVNC)." (PMID 31521203, 2019).
liver disease (2 papers, 2020). "Future studies may determine whether targeting SLC30A10 and SLC39A8 are possible therapeutic options to prevent liver disease in at-risk individuals." (PMID 32247823, 2020). "We identified novel associations between an MRI-derived measure of fibroinflammatory liver disease and variants in SLC30A10 and SLC39A8 that replicated with blood biomarkers of hepatocyte injury." (PMID 32247823, 2020). "The pathogenic role of SLC39A8 in liver inflammation and fibrosis is supported by studies in mice which provide mechanistic evidence for the critical role of ZIP8 in liver disease." (PMID 32247823, 2020).
pneumococcal pneumonia (2 papers, 2022 to 2023). A febrile disease caused by STREPTOCOCCUS PNEUMONIAE. "Based on this, our laboratory created a novel myeloid-specific Slc39a8(-/-) knockout (ZIP8KO) mouse model and determined whether ZIP8 loss altered host protection against pneumococcal pneumonia via changes in the gut microbiota." (PMID 37242309, 2023).
scoliosis (2 papers, 2018 to 2021). A congenital or acquired spinal deformity characterized by lateral curvature of the spine. "To understand the mechanism by which the SLC39A8 p.A391T allele leads to an increased risk of scoliosis, we investigated the clinical characteristics of patients harboring the risk allele." (PMID 30301978, 2018).
sleep disorder (2 papers, 2019 to 2023). A change from the patient's baseline sleeping pattern, in the hours slept and/or an alteration/dysfunction in the stages of sleep. "SLC39A8 facilitates the transport of drugs for treating anxiety, panic attacks, sleep disorders, agitation, and behavioral anomalies." (PMID 37759556, 2023).
type 2 diabetes (2 papers, 2020 to 2021). "cT1-increasing alleles at 4 variants (in SLC30A10, SLC39A8, TM6SF2, and PNPLA3) were associated with higher ALT and AST (all with p values <2×10−5) and higher risk of type 2 diabetes (all with p <0.002, except the SLC30A10 variant)." (PMID 32247823, 2020).
adolescent idiopathic scoliosis (1 paper, 2018). A scoliosis with no known cause arising in adolescent. "We identified a highly significant association between a coding variant in the manganese transporter SLC39A8 and risk of adolescent idiopathic scoliosis." (PMID 30301978, 2018).
allergic asthma (1 paper, 2023). A asthma with a basis in a pathological type I hypersensitivity reaction. "Among them, SLC39A8, ALOX15, and CA2 showed higher expression, while SLC40A1 and C3 exhibited lower expression in patients with allergic asthma." (PMID 37123407, 2023).
atherosclerosis (1 paper, 2013). A disease characterized by the build-up of fatty material and calcium deposition in the arterial wall resulting in partial or complete occlusion of the arterial lumen. "SLC39A8 expression level was positively correlated to plaques and smoking was positively correlated to all the genes in the cluster, suggesting that an up-regulation of genes of the cluster was associated to increased atherosclerosis extent." (PMID 23372645, 2013). "In addition to being connected to plaques, SLC39A8 was directly connected to HDL-cholesterol in the network, a result consistent with the association found with SLC39A8 genetic variants and supporting a causal role of SLC39A8 in atherosclerosis." (PMID 23372645, 2013). "Additionally, SLC39A8 was negatively correlated to HDL-cholesterol levels (∼1 probability), which is consistent with the protective role of HDL-cholesterol in atherosclerosis." (PMID 23372645, 2013).
cerebral malaria (1 paper, 2025). A sequestration of Plasmodium falciparum in the brain, which can cause coma and/or seizures. "A recent study applied network analysis and differential expression to whole-blood profiles, highlighting nine key host genes (including MBP, SAMSN1, PSMF1, SLC39A8) strongly linked to cerebral malaria." (PMID 41002937, 2025).
coeliac disease (1 paper, 2020). "Among those outliers, the SNPs rs7764984 (near HIST1H2BJ) and rs13107325 (near SLC39A8) were associated with three traits that putatively influenced the outcome: self-reported coeliac disease, body composition (impedance of leg) and memory function." (PMID 32081875, 2020).
colon cancer (1 paper, 2021). "In this study, we revealed the prognostic value of iron metabolism-related genes SLC48A1 and SLC39A8 in colon cancer; however, their associated signaling pathways need to be further explored." (PMID 35118074, 2021). "Immunohistochemistry showed that the SLC39A8 level was downregulated in colon cancer tissues, and the SLC48A1 level was upregulated significantly in colon cancer tissues." (PMID 35118074, 2021). "Knocking down SLC39A8 promoted the proliferation of different colon cancer cell lines (DLD1, HCT116, and HT29), and silencing SLC48A1 suppressed the proliferation of colon cancer cells in vitro." (PMID 35118074, 2021). "In different datasets of patients with colon cancer, SLC48A1 and SLC39A8 gene markers showed good prognostic performance." (PMID 35118074, 2021). "Next, we analyzed the potential function of SLC39A8 and SLC48A1 in colon cancer." (PMID 35118074, 2021). "Furthermore, the mRNA levels of SLC39A8 and SLC48A1 were successfully knocked down using siRNA in colon cancer cells in vitro." (PMID 35118074, 2021). "SLC39A8 and SLC48A1 play a role in the development of colon cancer and might be potential therapeutic targets." (PMID 35118074, 2021).
duodenal carcinoma (1 paper, 2024). "Thus, although there is a modest increase in sensitivity to cisplatin, the change may not be robust enough to suggest that SLC39A8 overexpression alone is a key determinant of cisplatin response in duodenal carcinoma cells." (PMID 39596116, 2024).
dwarfism (1 paper, 2017). "Individuals with SLC39A8/ZIP8 mutations develop cranial asymmetry, infantile spasms, and dwarfism, along with undetectable blood manganese levels and severe deglycosylation of blood proteins." (PMID 28617866, 2017).
familial cardiomyopathy (1 paper, 2017). An instance of cardiomyopathy that is caused by an inherited modification of the individual's genome. "All candidate genes but one (SLC39A8) exhibit preferential expression in striated muscle tissues and mutations in TTN, BAG3, FLNC and FHOD3 are known to cause familial cardiomyopathy." (PMID 28296976, 2017).
fibromyalgia (1 paper, 2023). A chronic disorder of unknown etiology characterized by pain, stiffness, and tenderness in the muscles of neck, shoulders, back, hips, arms, and legs. "Several genes/loci have been reported more than once in CWP, fibromyalgia, and MCP, including EXD3, SLC39A8, AMIGO3/GMPPB/RNF123, C6orf106, FAF1, SLC24A3, and LINC01065/LINC00558." (PMID 37144689, 2023).
lung squamous cell carcinoma (1 paper, 2020). "No direct relation of NSUN2 and SLC39A8 with lung squamous cell carcinoma (LUSC) has been known so far." (PMID 32854705, 2020).
malaria (1 paper, 2021). Malaria is a serious and sometimes fatal disease caused by a parasite that commonly infects a certain type of mosquito which feeds on humans. "Another key gene, SLC39A8, has been reported associated with malaria susceptibility." (PMID 33942992, 2021). "Among nine key genes, four genes (SAMSN1, SLC39A8, SMPDL3A, and FABP5) were positively correlated with malaria severity and upregulated in CM." (PMID 33942992, 2021). "Within the nine genes, five genes (MBP, SAMSN1, PSMF1, SLC39A8, and EIF3B) were previously found to be involved in malaria, and the remaining four genes (SMPDL3A, FABP5, SPSB3, and SHARPIN) were identified for the first time in the current study." (PMID 33942992, 2021). "SAMSN1, SLC39A8, SMPDL3A, and FABP5 were positively correlated with malaria phenotype/severity and showed an upregulation in the CM group compared with healthy controls, while MBP, SPSB3, PSMF1, SHARPIN, EIF3B were negatively correlated with malaria severity and downregulated in the DEG." (PMID 33942992, 2021).
multiple sclerosis (1 paper, 2024). A progressive autoimmune disorder affecting the central nervous system resulting in demyelination. "Furthermore, our phenotype-wide association study highlighted genes like SLC39A8 and EHBP1’s associations with fluid intelligence and HFEs linked to multiple sclerosis and liver-related diseases." (PMID 38956042, 2024).
psychotic disorder (1 paper, 2022). An abnormal condition of the mind that involves a loss of contact with reality. "This association with SLC39A8 could indicate that the ALCP-specific contains variance that is not unique to alcohol (e.g., risk for internalizing or psychotic disorders)." (PMID 36180423, 2022).
renal fibrosis (1 paper, 2026). A final common manifestation of a wide variety of chronic kidney diseases characterized by glomerulosclerosis and tubulointerstitial fibrosis. "Our recent work shows that kidney-specific SLC39A8 knockout (KKO) mice (reduced zinc uptake) exhibit milder AKI (ischemia–reperfusion and rhabdomyolysis) and CKD (ureteral obstruction and 5/6 nephrectomy), with lower serum creatinine/blood urea nitrogen (BUN) levels and reduced renal fibrosis." (PMID 41531895, 2026).
tobacco use disorder (1 paper, 2022). "Three novel genes—SLC39A8, GRK4 and HGFAC—within loci associated with altered alcoholic drinks per week (ADW) or cigarettes per day (CPD) were selected to further study their role in alcohol and tobacco use disorder." (PMID 35661789, 2022).